TBX19 (T-box transcription factor 19)
Description:
Transcriptional regulator involved in developmental processes. Can activate POMC gene expression and repress the alpha glycoprotein subunit and thyroid-stimulating hormone beta promoters.
Synonyms: TPIT; dj747L4.1; TBS19
Tractability: PROTAC: ubiquitination databases record sites on it.
Gene: Protein-coding gene on chromosome 1 (168,280,877 to 168,314,426, forward strand). Ensembl gene ENSG00000143178.
Subcellular location: Nucleus
Subcellular location (Human Protein Atlas): Nuclear speckles
Gene Ontology:
Molecular function: protein binding; sequence-specific double-stranded DNA binding; DNA-binding transcription factor activity, RNA polymerase II-specific; RNA polymerase II cis-regulatory region sequence-specific DNA binding; cis-regulatory region sequence-specific DNA binding; DNA binding; DNA-binding transcription activator activity, RNA polymerase II-specific; DNA-binding transcription factor activity
Biological process: anatomical structure morphogenesis; cell fate specification; heart morphogenesis; mesoderm formation; regulation of transcription by RNA polymerase II; positive regulation of DNA-templated transcription; positive regulation of transcription by RNA polymerase II; regulation of DNA-templated transcription
Cellular component: chromatin; nucleus
Genetic constraint (gnomAD): Loss-of-function variants: 32 observed, 44.13 expected, observed/expected ratio (o/e) 0.73, 90% interval 0.55 to 0.97. The upper end of that interval is the gene's LOEUF score, 0.97, which puts it in group 4 of 6, group 1 being the genes least tolerant of losing a copy. Missense variants: 494 observed, 603.67 expected, observed/expected ratio (o/e) 0.82, 90% interval 0.76 to 0.88. Synonymous variants: 220 observed, 236.82 expected, observed/expected ratio (o/e) 0.93, 90% interval 0.83 to 1.04.
Homologues: Orthologues: chimpanzee TBX19 (100% identical), macaque TBX19 (98% identical), pig TBX19 (93% identical), rabbit TBX19 (92% identical), mouse Tbx19 (92% identical), guinea pig TBX19 (90% identical), rat Tbx19 (90% identical), dog TBX19 (86% identical), zebrafish tbx19 (58% identical), Drosophila melanogaster mid (23% identical), Drosophila melanogaster H15 (23% identical), Caenorhabditis elegans mab-9 (22% identical), and 8 more. Paralogues in human: TBXT (53% identical), TBX18 (28% identical), TBX2 (28% identical), MGA (27% identical), TBR1 (27% identical), TBX15 (27% identical), TBX5 (26% identical), TBX3 (26% identical), EOMES (26% identical), TBX4 (26% identical), TBX21 (25% identical), TBX1 (25% identical), and 4 more.
Diseases named in the same sentence as TBX19 in open-access papers:
TBX19 is named in the same sentence as 40 diseases in open-access papers, as found by Europe PMC text mining. Sharing a sentence is not in itself a finding about the gene and the disease. The quoted sentences say what the papers report.
pituitary adenomas (15 papers, 2018 to 2025). "Silent pituitary adenomas immunostain for ACTH and TBX19 (silent corticotroph adenomas), or for PRL, or GH, and POU1F1 (silent lactotroph or somatotroph adenomas, respectively)." (PMID 38612778, 2024). "Functioning (FCA) and silent corticotroph (SCA) pituitary adenomas act differently from a clinical perspective, despite both subtypes showing positive TBX19 (TPIT) and/or adrenocorticotropic hormone (ACTH) staining by immunohistochemistry." (PMID 33066652, 2020). "Consistent with the histologic differentiation, the M6 pituitary adenoma showed massive upregulation of POU1F1 and PITX1, high overexpression of PITX2 and NR4A1-3, but minimal or absent expression of TBX19 and NR5A1, respectively." (PMID 35978432, 2022).
adenoma (14 papers, 2013 to 2025). A neoplasm arising from the epithelium. "Thus, NR5A1-, POU1F1- and TBX19-derived adenomas shared the same expression level of most genes encoding the different cyclins, CDK and CDK inhibitors." (PMID 35260162, 2022). "In contrast, the expression of the different genes encoding cyclins, CDK and CDK inhibitors among NR5A1-, POU1F1- and TBX19-adenomas showed only subtle differences." (PMID 35260162, 2022). "TBX19-derived tumors, which consist of ACTH-secreting adenomas, had the lowest number of differentially expressed cyclin, CDK and CDK inhibitor genes." (PMID 35260162, 2022). "By contrast, the expression of genes that encode cyclins and CDK and CDK inhibitors among TBX19, NR5A1, and POU1F1 adenomas is not so different." (PMID 36968144, 2023). "Several of the genes encoding kinase presented isoforms, resulting from alternative splicing of mRNA: kinases PAK7 and STK26 in NR5A1-derived tumors, kinase PPIP5K2 in POU1F-derived adenomas and kinases like PPIP5K2 and kinases WEE1 and STK17 in the TBX19 tumors." (PMID 35260162, 2022).
corticotroph adenomas (11 papers, 2018 to 2025). "Intriguingly, we revealed distinct groups as follows: 1) somatotroph adenoma: high POU1F1 and high DLK1; 2) lactotroph adenoma: high POU1F1 and low DLK1; 3) gonadotroph adenoma: high FSHB and low DLK1, followed by high GATA2 and low DLK1; and 4) corticotroph adenoma: high TBX19 and low DLK1." (PMID 33472171, 2020). "Based on the transcriptomic analysis of 172 PitNETs, we suggest a solution as follows: 1) somatotroph adenoma: high PIT1 and high DLK1; 2) lactotroph adenoma: high PIT1 and low DLK1; 3) gonadotroph adenoma: high FSHB and low PIT1/DLK1; and 4) corticotroph adenoma: high TBX19 and low PIT1/DLK1." (PMID 33472171, 2020). "We present, in a large cohort of corticotroph adenoma, that gene expression of known corticotroph cell markers, POMC, TBX19, and PSCK1 was higher in the functioning group, in accordance with previous reports." (PMID 33066652, 2020).
pituitary tumor (4 papers, 2019 to 2025). A benign or malignant neoplasm affecting the pituitary gland. "Silent corticotroph tumors account for ~30% of all corticotroph tumors and 10–20% of silent pituitary tumors and originate from a TBX19/Tpit expressing cell lineage." (PMID 40565361, 2025).
Obesity (3 papers, 2016 to 2024). Accumulation of substantial excess body fat. "TBX19 variants have been linked to both obesity and neonatal hypoglycemia." (PMID 38781157, 2024). "The genes found to be positively selected in Enshi pigs are involved in crucial biological processes such as body size and immunity (RPS10 and VASN), obesity (GSK3), male fertility (INSL6), and early development (TBX19)." (PMID 27808243, 2016).
colorectal cancer (2 papers, 2019 to 2023). A primary or metastatic malignant neoplasm that affects the colon or rectum. "TBX19 was shown to be more highly expressed in colorectal cancer tissue, which was associated with lymph node metastasis." (PMID 31223310, 2019). "TBX19 itself has not been implicated in melanoma, but it has been linked to lymph node metastasis in colorectal cancer and TBX2, another member of the T-Box family, is involved in melanoma proliferation." (PMID 36894939, 2023).
Hypoglycemia (2 papers, 2017 to 2024). A decreased concentration of glucose in the blood. "All neonates with TBX19 mutations developed neonatal hypoglycemia and had complete IAD, but the incidences of these and other clinical signs (e.g., long-term cholestatic jaundice and seizures) were lower in the two groups without TBX19 mutations." (PMID 39664280, 2024).
Cognitive impairment (1 paper, 2022). Abnormal cognition is characterized by deficits in thinking, reasoning, or remembering. "Indeed, one of the main consequences of undiagnosed adrenal crises and inadequately adjusted hydrocortisone treatment in IAD due to TBX19 mutations is cognitive impairment." (PMID 36890856, 2022).
colon adenoma (1 paper, 2023). An adenoma that arises from the colon. "Recent research has shown that TBX19 gene, which is increased in colon adenomas, was identified as one of the genes triggered by KRAS mutations." (PMID 36999050, 2023).
microcephaly (1 paper, 2022). A congenital or acquired developmental disorder in which the circumference of the head is smaller than normal for the person's age and sex. "Extrapituitary malformations, including a Chiari I malformation and microcephaly, have been reported in other cases of TBX19 mutation." (PMID 36890856, 2022).
prostate carcinoma (1 paper, 2024). A carcinoma that arises from epithelial cells of the prostate gland. "This research provides comprehensive evidence that chimeric SFT2D2‐TBX19 promotes prostate cancer progression by encoding the TBX19‐202 protein and stabilizing mitochondrial ATP synthase via ATP5F1A phosphorylation." (PMID 39540264, 2024). "Additionally, SFT2D2‐TBX19 could also encode TBX19‐202, which shares a similar oncogenic role with the parental TBX19 in promoting the progression of prostate cancer." (PMID 39540264, 2024). "Both the parental TBX19 and the TBX19‐202 peptides contribute to prostate cancer progression through molecular pathways such as DNA duplication, cell cycle, and TNF signaling." (PMID 39540264, 2024). "Knockdown of parental TBX19 inhibited prostate cancer cell proliferation, colony formation, migration and invasion." (PMID 39540264, 2024). "Both TBX19‐202 and its parental TBX19, which share homologous amino acid sequences, enhance prostate cancer cell proliferation, migration, and invasion." (PMID 39540264, 2024). "In summary, SFT2D2‐TBX19 could encode TBX19‐202, which shares a similar oncogenic role with the parental TBX19 in promoting the progression of prostate cancer." (PMID 39540264, 2024). "Notably, when comparing the transcript levels of chimeric SFT2D2‐TBX19 RNA and parental TBX19 RNA using PCR standard amplification curves, the transcript number of parental TBX19 was 102–103 times higher than that of chimeric SFT2D2‐TBX19 in six prostate cancer cell lines." (PMID 39540264, 2024). "Given that the expression level of SFT2D2‐TBX19 was significantly lower than that of TBX19, and TBX19 itself was observed to promote prostate cancer development, we speculated that the SFT2D2‐TBX19 lncRNA may possess distinct molecular functions beyond encoding TBX19‐202." (PMID 39540264, 2024).
Respiratory tract infection (1 paper, 2017). An infection of the upper or lower respiratory tract. "Here, we presented a new mutation in the TBX19 gene in a patient with CIAD who presented with recurrent respiratory tract infections." (PMID 28458651, 2017).
somatotrophinomas (1 paper, 2022). "Clinically functioning PA comprise POU1F1-lineage derived tumors (GH-secreting somatotrophinomas, PRL-secreting prolactinomas and the rare TSH-secreting thyrotrophinomas) and the TBX19 lineage derived, ACTH-secreting corticotrophinomas." (PMID 35260162, 2022).
tumor (36 papers, 2019 to 2026). "Overexpression of TBXT, TBX15, and TBX19 causes tumor invasion, migration, and metastasis." (PMID 38965548, 2024). "The results indicated that SFT2D2‐TBX19 lncRNA contributed approximately 60–70% to tumor cell development, while TBX19‐202 accounted for about 30–40%." (PMID 39540264, 2024). "The up-regulated DEGs in TBX19+ tumor cells were related to apoptotic signaling pathways and vesicle-mediated transport." (PMID 38658971, 2024). "Corticotroph tumours were characterized by tumours stained positively for T-box family member TBX19 (TPIT), while gonadotroph tumours were characterized by positivity for steroidogenic factor (SF-1)." (PMID 38756997, 2024). "The gene encoding this receptor, was also found to be upregulated in TBX19 tumors, as was the gene encoding MERTK which seems to play an important role in tumor proliferation, survival and migration." (PMID 35260162, 2022). "Particularly, the G1 and G1/S transition expression profiles differentiates better the NR5A1 from the POU1F1 and TBX19 tumor lineages, supporting the observation of the cyclins and CDK expression where CNFPA present more proliferation than the other tumors." (PMID 35260162, 2022). "Flow-cytometric analysis showed the presence of different pituitary lineages (which may originate from the tumor and/or adjacent tissue), as well as enrichment of the TBX19+ (corticotrope) lineage and stem cells (marked by SOX2, CXCR4 and CD133), similar to the patient’s tumor." (PMID 37614709, 2023). "The results demonstrated that CX3CR1+, C1Q+, and GPNMB+ macrophages exhibited the highest interaction with NR5A1+, TBX19+, and POU1F1+ tumor cells, respectively." (PMID 38658971, 2024). "Despite the tumor cells which were annotated based on lineage-specific transcription factors, namely POU1F1+, TBX19+, and NR5A1+ tumor cells, every cell type appeared across the three lineages." (PMID 38658971, 2024). "After 5 weeks, the tumor organoids (referred to as tumoroids), shown to contain corticotrope (ACTH+), stem/progenitor (SOX2+) and intermediate (PITX1+, TBX19+) cell populations, were moved to spinner flasks, which further increased ACTH production." (PMID 37614709, 2023). "Immunohistochemistry analyses identified that PIT1 cell lineage marker dominates in four PitNETs, gonadotroph PitNET marker NR5A1 (SF1) is the most abundant in five tumours and corticotroph cell lineage marker TBX19 (TPIT) has highest expression in one PitNET." (PMID 36026497, 2022). "However, this scenario was not effective in our pancreatic ACTH-secreting tumor sample, where the absence of TBX19 and PITX1 overexpression points to alternative mechanisms driving the expression of POMC." (PMID 40002253, 2025). "This immune gene signature segregates along each tumor lineage and the transcription factor that determines their terminal differentiation: POU1F1-dependent GH-, TSH-, PRL-secreting PitNET; NR5A-1-driven gonadotrophinomas; and TBX19-dependent ACTH-secreting PitNET." (PMID 38790160, 2024). "ANKRD36BP1 (dist = 3,795), TBX19 (dist = 29815) chr1:168220463A > I (p < 0.001), HOOK3 chr8:42883441A > I (p = 0.0011), PGPEP1 chr19:18476416A > I (p < 0.001), and NDUFV3 chr21:44329452A > I (p = 0.038) were significantly different between tumor and normal tissues." (PMID 36999050, 2023).
cancer (3 papers, 2019 to 2024). A tumor composed of atypical neoplastic, often pleomorphic cells that invade other tissues. "Meanwhile, it was also reported that TBX19 acts downstream of KRAS in human cancer." (PMID 31223310, 2019).
TBX19 also shares sentences with these, for which no sentence is quoted: somatotroph adenoma (4 papers); Adrenocorticotropic Hormone Deficiency (2); gonadotroph adenoma (2); lactotroph adenoma (2); thyrotroph adenoma (2); autosomal recessive disease (1); benign tumors (1); craniopharyngioma (1); Cushing syndrome (1); glioma (1); hypophysitis (1); liver cancer (1); melanoma (1); metastasis (1); metastatic tumor (1); Neonatal hypoglycemia (1); neuroendocrine tumors (1); osteoporosis (1); pituitary deficiencies (1); prostate tumor (1); Sepsis (1); somatotroph tumors (1); type 2 diabetes mellitus (1); upper respiratory tract infection (1); viral meningitis (1).